TNF (tumor necrosis factor)
Diseases named in the same sentence as TNF in open-access papers (continued):
Sharing a sentence is not in itself a finding about the gene and the disease.
colitis (continued). "IPA alleviates DSS-induced colitis by increasing tight junctions and the muc2-influenced mucus barrier via Pregnane X Receptor (PXR), thereby promoting intestinal barrier integrity while inhibiting TNF-α secretion." (PMID 37389342, 2023). "In this study, the oxidative injury caused by colitis preceded the inflammatory damage, once the levels of MPO, TNF-α, and IL-10 did not change." (PMID 37577725, 2023). "The authors used TNF-α-stimulated NCM460 cells and a DSS-induced C57BL/6 mice model of colitis." (PMID 37367886, 2023). "Oral QT-loaded silk fibroin nanoparticles (QSFN) can produce obvious intestinal anti-inflammatory properties by down regulating proinflammatory cytokines (TNF-α, IL-1β, IL-6, MCP-1, ICAM-1, NLRP3, iNOS) and significantly reducing the DAI score of DSS-induced colitis mice." (PMID 37033644, 2023). "Due to a number of studies that have shown a link between increased TNFα levels and pathogenesis of IBD, as well as the therapeutic potential of anti-TNFα therapy and soluble TNFα receptors, we sought to investigate the role of macrophage-secreted TNFα and OJS administration in colitis." (PMID 37049400, 2023). "In our study, L. sakei CVL-001 administration led to decreased gene expression levels of pro-inflammatory cytokines, such as IL-1β, TNF-α, and IL-6, and increased gene expression levels of anti-inflammatory cytokines, such as IL-10, against DSS-induced colitis." (PMID 37317332, 2023). "In addition, other research has proved that AG ameliorates colitis in DSS-induced colitis mice and HCT-116 and HT-29 cells by alleviating the shortening of the colon and suppressing inflammation by down-regulating the expression of TNF-α, IL-6, and IL-8." (PMID 37920216, 2023). "Our study showed that the newly isolated C4 strain could effectively reduce the expression levels of IL-1β, IL-6, and TNF-α, and upregulate the expression levels of ZO-1 and occludin to alleviate the symptoms in DSS-induced colitis mice." (PMID 37152759, 2023). "Treatment with VAS2870 ameliorated DSS-induced colitis with a reduction in DAI, MPO levels, macroscopic and histological scores, secretion of proinflammatory cytokines (TNF-α, IL-6, and IL-1β), and an increase in colon length, which were not affected by SS treatment." (PMID 37239114, 2023). "Furthermore, the levels of inflammatory mediators and cytokines, including TNF-α, IL-1β, and IL-6, were significantly lower in the BCP group than those in the untreated DSS-induced colitis group." (PMID 36431883, 2022). "Not surprisingly, C3G inhibited NF-κB phosphorylation, reduced mRNA expression of pro-inflammatory cytokines including IL-1β, IL-6, IL-8, COX-2, and TNF-α, and protein levels of apoptosis related genes in DSS-induced colitis mice, providing new ideas for using C3G as adjuvant agent for treating UC." (PMID 35805952, 2022). "Furthermore, this finding is in accordance with our previous study, where the protein levels of TNF-α and TGF-β were found to be reduced upon CM exposure in a mouse model of colitis." (PMID 36289619, 2022). "Previous studies focused on the expression of IL-1β and TNFα as promising proinflammatory cytokines in the absence of mPGES-1 during colitis." (PMID 34983695, 2022). "Having established that CDK9 inhibition effectively suppresses IFN-γ and TNF-α production in CD4+ T cells, we reasoned that systemic delivery of CDK9i could abrogate experimental colitis." (PMID 35660024, 2022). "Furthermore, significantly low pro-inflammatory cytokine levels (TNF-α and IL-6) in the Cur-HA-PLGA-NP-treated group indicated colitis alleviation, which is generally high in chronic inflammation." (PMID 36297553, 2022). "In conclusion, our results revealed that oral administration of BCP in DSS-induced ulcerative colitis mice improved colitis by reducing MPO activity, IL-1β, IL-6, and TNF-α concentrations, as well as the abundance of bacteria that cause intestinal immune imbalance." (PMID 36431883, 2022).
colitis (continued). "Cyanidin-3-glucoside and cyanidin were reported to downregulate the proinflammatory mediator nitric oxide, as well as proinflammatory cytokines TNF-α, IL-1β, IL-6, and IFN-γ in 2,4,6-trinitrobenzenesulfonic acid (TNBS)-induced colitis mice and lipopolysaccharide (LPS)-stimulated Caco-2 cells." (PMID 35204188, 2022). "A significant increase in TNF levels in the hippocampus, but not cortex, of vehicle-treated colitis mice was observed, along with a depressive-like behavior assessed by the TST in this experimental group." (PMID 35295931, 2022). "T-TNF blockade during established colitis not only eliminated T-TNF, but also decreased levels of non-T cell-derived TNF possibly by limiting inflammation." (PMID 35383266, 2022). "We show that BBR suppresses the activation of macrophages and granulocytes in colitis mouse models, accompanied by decreases in the production of inflammatory cytokines including IL1β, TNFα, and IL6, yet, T cells are not significantly affected." (PMID 36528592, 2022). "T. halophilus administration to colitis mice reduced TNFα levels but was not statistically significant." (PMID 35741032, 2022). "Following this notion, conventionally housed TNFdeltaARE mice with a deletion in the TNF AU-rich (adenosin-uracil) elements (ARE) can develop colitis but do not exhibit indications of colon inflammation in SPF or germ-free facilities." (PMID 35836813, 2022). "Given that measurements of colonic explants reflects the abundance of soluble cytokines in the medium, our data further indicate that soluble TNF during colitis is likely be produced by non-T cells." (PMID 35383266, 2022). "In addition, ZBE inhibited TNF-α, IL-1β, and IL-12 by regulating the TLR4-and TLR4-related pathways in mice and LPS-induced cellular inflammation in DSS-induced experimental colitis." (PMID 36081930, 2022). "Moreover, GLPN with lower Mw fraction exhibited anti-inflammatory activity through preventing colon length shortening and inhibiting the production of pro-inflammatory cytokines including TNF-α, IL-1β, and IL-6 in DSS-induced colitis mice." (PMID 36245525, 2022). "AL-1 ameliorated DSS-induced colitis in mice by inhibiting NF-κB and MAPK signaling pathways, reduced iNOS, COX-2, NO and PGE2 in cultured macrophages, significantly reduced production of IL-1β, IL-6, TNF-α, PGE2 and IFN-γ, and increased secretion of IL-10." (PMID 36238575, 2022). "Our results showed that LCS-SeNPs reduced the pro-inflammatory cytokines TNF-α and IL-6 levels in serum and the colon of DSS-induced colitis mice, suggesting that LCS-SeNPs can achieve anti-inflammatory effects by reducing the serum levels of pro-inflammatory factors TNF-α and IL-6." (PMID 36555167, 2022). "Trefoil factors (TFF) and antitumor necrosis factor-α (TNF-α) nanobodies (single-domain antibody fragments) are among the therapeutic substances that have been constitutively expressed in L. lactis and tested in DSS-induced colitis in mice." (PMID 35628274, 2022). "Likewise, in a murine colitis model, treatment with a P2X7R antagonist, A438079, reduced the production of inflammatory cytokines, TNF and IL-1β, in colon tissue." (PMID 35492615, 2022). "Moreover, B. vulgatus Bv46 treatment reduced the expression of colonic TNF-α, IL-6 and IL-1β in the DSS-induced mouse colitis in vivo and the TNF-α, IL-6 and IL-1β release in the supernatants of LPS-activated macrophage cells in vitro." (PMID 36531989, 2022). "Exacerbated colitis, aggravated changes in colon length, MPO, TNF-α and IL-1β in gut tissue." (PMID 35893902, 2022). "For example, compared with those in the control group, mice with colitis showed longer-lasting immobility in the forced swimming test (FST), and higher expression levels of pro-inflammatory mediators (including TNF-α), iNOS expression, and nitrite content in the hippocampus." (PMID 36275694, 2022).
colitis (continued). "Han and colleagues reported that atractylenolide III (5, 10 mg/kg) could ameliorate DSS-induced colitis inflammatory and oxidative stress by regulating the MDA and GSH contents, SOD activity, and the expression of TNF-α, IL-6, COX-2, and iNOS mRNA." (PMID 36160392, 2022). "Thus, a significant increase in mRNA of TNF, IL-6, IL-1β, and ICAM-1 genes in the proximal colon in mice with DSS-induced colitis compared with control mice." (PMID 36359839, 2022). "Colitis rats induced by 5% DSS and supplemented with 100 mg LBP/kg bw for 4 weeks reduces serum lipid peroxidation substance MDA levels, colonic TNF-α, serum IL-6 levels, and the expression of pain signaling proteins TRPV1 and TRPA1 in the colon, and enhance serum antioxidative CAT activity." (PMID 35269566, 2022). "All the rats exposed to 3% DSS for 7 days developed acute colitis, as evidenced by the increase in the DAI, the shortening in the colon length, and the increase in the mRNA relative abundance of the pro-inflammatory cytokines IL-1β, IL-6, and TNF-α." (PMID 35628158, 2022). "Furthermore, CHR down-regulates LPS-elicited TNF-α, IL-6, and COX-2 expressions by suppressing the activation of NF-κB and Caspase-1, helping resist colitis." (PMID 35599576, 2022). "Previous studies have shown that the levels of TNF-α and IL-1β decreased in the NLRP3−/−mice with colitis, indicating that NLRP3 could regulate the release of inflammatory cytokines." (PMID 35745163, 2022). "In the Oral Clinical Trials for tofAcitinib in ulceratiVE colitis (OCTAVE) trials, tofacitinib induced remission more often than placebo in patients with moderate-to-severe UC who failed initial conventional therapy or anti-TNF therapy." (PMID 37168636, 2022). "Preclinical studies suggest that prophylactic TNF-α inhibition eliminated ICI-induced colitis without affecting anti-tumor response." (PMID 35432346, 2022). "Interestingly, immunomodulatory molecules, such as TNFα, are upregulated in both IBD and checkpoint-mediated colitis." (PMID 36612082, 2022). "Baicalin ameliorated TNBS-induced colitis injury by suppressing TLR4 signaling in a concentration-dependent manner, inhibiting NF-κB activation and limiting the inflammatory response, such as ICAM-1, MCP-1, Cox-2, TNF-α, IL-1β and IL-6." (PMID 35484567, 2022). "Caffeic acid showed the capacity to reduce the severity of bowel damage at histological and biochemical levels, suppressing inflammatory cytokines (i.e., TNF-α, IL-6, IFN-γ) secretion through the inactivation of NF-kB to reduce the T-cells colonic infiltration, significantly alleviating colitis." (PMID 35056616, 2022). "Ursolic acid inhibits the activation of NF-κB and MAPK signaling pathways in IECs and macrophages, reduces TNF-α, IL-1β, COX-2, and iNOS in TNBS-induced colitis in mice as well as in LPS-stimulated inflammatory cells expression levels and attenuate the inflammatory response." (PMID 35873579, 2022). "Evelyn Saba and colleagues found that ginsenoside Rg3 (20 mg/kg) could decrease the expression of pro-inflammatory mediators and cytokines including NO, IL-1β, IL-5, IL-13, and TNF-α, and levels of NLRP3 inflammasome in DSS-induced colitis mice." (PMID 36160392, 2022). "Therefore, we supposed that crocetin reduced the level of TNF-α in serum result in worsened inflammation and delayed recovery in DSS-induced colitis mice." (PMID 35409192, 2022). "Similarly, mice with acute and chronic colitis, induced by DSS had reduced TNF-α, as well as inhibited Th1 and Th17 proliferation responses, when treated with CM." (PMID 35493477, 2022). "PCN activation of PXR can protect DSS-induced colitis that is due to the activation of phase II enzymes and efflux transporters (e.g., GSTa1, MDR1a and MRP2), which can reduce the proinflammatory cytokines IL-6, TNF-α, MCP-1, and IL-1α expression." (PMID 35600949, 2022).
colitis (continued). "In the present study, except for the obvious UC symptoms, we observed an increase in pro-inflammatory cytokines (TNF-α, IL-6) and MPO activity as well as a decrease in anti-inflammatory cytokines such as IL-10, which are closely related to the severity of colitis." (PMID 36295859, 2022). "Next, we compared levels of TNF-α and IL-6 in colitis mice in the presence and absence of MBZ using ELISA assay." (PMID 35715495, 2022). "A study reported that glycyrrhetic acid (10, 50 mg/kg) could decrease the levels of IL-6, IL-1β, and TNF-α, and suppress the expression of COX-2, NF-κB, and PGE2 protein for treating the DSS-induced colitis mice." (PMID 36160392, 2022). "Colitis was reversed by depleting colitogenic T cells with anti-CD4 antibodies, leading to decreased leukocyte infiltration to sites of inflammation and reduced serum and colonic TNF-α concentrations." (PMID 35939430, 2022). "(100, 300 mg/kg) could improve the syndrome of TNBS-induced colitis mice by regulating the MPO and MDA contents and the levels of pro-inflammatory (TNF-α, IL-6, L-1β, IL-12, IFN-γ, IL-2, IL-17) cytokines and anti-inflammatory cytokines (IL-4, IL-10)." (PMID 36160392, 2022). "Intriguingly, compound 13b at a low dose decreased the levels of IL-17 and TNF-α but did not alleviate the symptoms of colitis." (PMID 36077306, 2022). "Also, chromium supplementation improved histological findings, upregulated IL-10, and downregulated TNF-α, and IFN-γ in experimental colitis." (PMID 36570124, 2022). "By contrast, the expression of Il1β, Ifng, and TNF-α (Tnf) was significantly decreased by L. reuteri treatment during DSS-induced colitis (p < 0.05) without affecting Il6 or Il10 levels (p > 0.05)." (PMID 35320932, 2022). "Acetic acid-induced colitis in rats showed a significant increment (P < 0.0001) in IL-1β and TNF-α levels compared with the negative control group." (PMID 35428860, 2022). "Experimentally, treatment with yeast worsened the DAI in DSS colitis and exacerbated ASCA levels, in addition promoted serum and colonic tissue pro-inflammatory cytokine secretion (TNF- α, IL-1β and IL-6) and stimulated the expression of NF-κB in colonic tissue." (PMID 36384756, 2022). "Moreover, the effect of LCS-SeNPs on intestinal oxidative stress and permeability were evaluated by measuring the levels of TNF-α, IL-6, GSH-Px, LPS and DAO in the serum of mice with DSS-induced colitis." (PMID 36555167, 2022). "Furthermore, synthetic, disulfide-rich peptides based on ES products of A. caninum and N. americanus, reduced colitis symptoms in a TNBS model and suppressed CD4 + T cell proliferation and inhibited IL-2 and TNF production." (PMID 36186812, 2022). "However, when NOS inhibitors were used to prevent iNOS and nitrite production, mice with colitis had a shorter rest time in FST, lower TNF-α and nitrite levels in the hippocampus, and reduced inflammatory injury in the hippocampal region." (PMID 36275694, 2022). "While reduced TNF expression is consistent with the immunomodulatory effects of HF reported in colitis, it is unclear why levels of IL-6 and IL-10 are not similarly affected." (PMID 35296081, 2022). "Also, in other studies, serum TNF-α level was decreased in obese mice fed a high-fat diet supplemented with RB compared to obese mice, and γ-oryzanol significantly reduced the up-regulated expression of IL-1β, IL-6, TNF-α, and COX-2 mRNA in mice with colitis." (PMID 34636986, 2022). "In addition, the plasma levels of granulocyte colony-stimulating factor (G-CSF), IL-6, IL-17, TNF-α, and chemokine ligand 1 (CXCL1) were significantly increased in the colitis model." (PMID 36009796, 2022). "Inhibited TNF-α, iNOS, MMP-3, MMP-9 mRNA Expressions in colonic tissue of a colitis model." (PMID 35208860, 2022). "Thus, the present study was performed to investigate the effects of FREG on protecting the intestinal barrier function in TNF-α﻿ induced epithelial barrier dysfunction in human Caco-2 cells and in TNBS induced colitis rats." (PMID 35130890, 2022).
colitis (continued). "Trim27 deficiency could decrease the levels of pro-inflammatory cytokines (IL-6, TNF-α, and IL-17A) in the colonic mucosa and suppress the DSS-induced colitis." (PMID 35565775, 2022). "In addition, FREG regulated the tight junction proteins, and markedly decreased TNF-α, MPO levels and significantly increased the secretory IgA levels in TNBS induced colitis rats." (PMID 35130890, 2022). "As for colitis, it has been shown that TRM cells are increased in the gut of patients with IBD and have a pro-inflammatory phenotype that CD69+ T cells expressed higher levels of IFNγ, IL-13, IL-17A, and TNF mRNA than CD69− T cells." (PMID 35844584, 2022). "Increased hippocampal expression of TNF-α has been noted in DNBS, TNBS, and DSS-induced colitis." (PMID 34983592, 2022). "The results showed that ERE treatment alleviated DSS-induced colitis, which was characterized by decreases in disease activity index (DAI) scores, spleen index and colon levels of TNF-α and IL-6, mitigation in pathological damage and oxidative stress and increases in colon length and IL-10 levels." (PMID 36295859, 2022). "Moreover, oral gavage of ampicillin induced colitis: it increased colon shortening, myeloperoxidase activity, and IFN-γ and TNF-α expression and reduced IL-10 expression in the colon." (PMID 34667205, 2021). "FCPS treatment could ameliorate colitis symptoms by restoring the expression of light junction protein claudin-1 and down-regulating the level of TNF-α and IL-1β in the DSS-induced colitis mice." (PMID 34199820, 2021). "Furthermore, CMP33 significantly reduced the release of pro-inflammatory cytokines (TNF-α, IL-6, L-1β, IL-12, IFN-γ, IL-2, and IL-17), whereas triggered anti-inflammatory factors IL-4 and IL-10 in the colon tissue and serum of colitis mice." (PMID 33981232, 2021). "The mice develop (histological) inflammation at the axial and peripheral entheses 1 week after curdlan induction followed by development of clinical enthesitis, sacroiliitis, peripheral arthritis and colitis and uveitis with increased serum levels of IFN-γ, TNF-α, IL-6 and IL-17A." (PMID 34267743, 2021). "Upon oral administration, the Map4k4 siRNA, encapsulated in galactosylated trimethyl chitosan-cysteine (GTC)/tripolyphosphate (TPP) or GTC/HA NPs, significantly decreased the expression of TNF-α in colonic cells and related parameters in the DSS-induced colitis in a mouse model." (PMID 35052764, 2021). "In DSS-induced colitis mice treated with miR-19a mimic, colon tumor numbers, sizes and tumor loads are higher compared to the control group; pro-inflammatory cytokines, including IL-1β, IL-6, IL-17a, IFN-γ and TNF-α are also upregulated." (PMID 33921348, 2021). "Surprisingly, 25 patients in our study sequentially used three different types of TNFα inhibitors, which is not in accordance with guidelines of the American College of Rheumatology and the European Crohn ́s and Colitis Organisation." (PMID 34302442, 2021). "The rodents with colitis induced by the administration of trinitrobenzenesulfonic (TNBS) acid exhibited intensification of the inflammatory changes and increased synthesis of IL-1β and TNF-α, following having been infected with fungi of the genus Candida." (PMID 34578152, 2021). "In this study, a TNF-α-targeted US contrast agent, MBTNF-α, was developed, and ex vivo intracolic USMI experiments using MBTNF-α were successfully conducted to accurately quantify mTNF-α expression in colons excised from a murine model of colitis." (PMID 34556023, 2021). "7-hydroxyfrullanolide was also tested in different animal inflammation models, in which oral administration dose-dependently diminished the induced and spontaneous production of TNF-α along with IL-6 in a BALB/c ear edema model and in DSS-induced colitis in mice." (PMID 34208907, 2021).